BRAF (B-Raf proto-oncogene, serine/threonine kinase)
Diseases named in the same sentence as BRAF in open-access papers (continued):
Sharing a sentence is not in itself a finding about the gene and the disease.
colorectal cancer (continued). "Thus, ZEB1 can function as a tumor suppressor in BRAF-mutant colorectal cancer, which highlights the importance of analyzing the KRAS/BRAF mutational background in this disease." (PMID 38139138, 2023). "However, targeted therapy combined with immune checkpoint blockade therapy seems to bring light to BRAF mutant colorectal cancer patients." (PMID 37302081, 2023). "Moreover, 11 patients (17%) were in the colorectal cancer profile, with RAS and BRAF gene mutations detected in 2 and 1 of them, respectively." (PMID 36899286, 2023). "Surprisingly, a high level of PD-L1 expression in MSS colorectal cancer cell lines (DiFi) was induced by BRAF V600E, suggesting that PD-L1 expression may not only exist in MSI-H BRAF-mutated CRC." (PMID 37302081, 2023). "AI applied to radiologic images, called radiomics, was also evaluated to predict the MSI status in colorectal cancer with no exploration of BRAF and KRAS mutation status." (PMID 38201408, 2023). "Furthermore, colorectal cancer is a highly heterogeneous clinical entity; genetic KRAS, NRAS, BRAF, or HER2 genes also work as the critical diagnostic and prognostic biomarkers." (PMID 36831695, 2023). "However, pre-existing BRAF-amplified cells (∼4%) have been reported in drug-naïve colorectal cancer cells." (PMID 36267209, 2022). "For example, for common tumours such as colorectal cancer where there is an ever-expanding list of clinically relevant biomarkers (e.g., BRAF V600E, MMR, HER2, POLE, KRAS G12C, NTRK), each patient subset represents only a small proportion of the overall population." (PMID 36077668, 2022). "Interestingly, these POLE mutations were predominantly associated with KRAS, NRAS, BRAF, and/or PIK3CA mutations, commonly found in colorectal cancers." (PMID 35624529, 2022). "Although not all BRAF mutated colorectal cancers are MSI high, the association of BRAF mutations with MSI and CIMP has been previously reported and MSI is commonly the result of MLH1 suppression through promoter methylation in cancers with BRAF mutations." (PMID 36079062, 2022). "In contrast, colorectal cancers with PIK3CA mutations but without BRAF mutations have statistically significant lower MSI, TMB, and CIMP rates and higher CIN rates compared with double mutants." (PMID 36079062, 2022). "Similarly, in a “real life” cohort of BRAF mutant metastatic colorectal cancers treated with targeted therapies as used in the BEACON trial in several Italian centers, the prevalence of MSI or Mismatch Repair deficiency was 15%." (PMID 36079062, 2022). "Only 2 colorectal cancer cell lines with BRAF mutations RKO and HT-29 show MYC amplifications and both are more sensitive to the NUAK inhibitor WZ4003 than the mean sensitivity of the BRAF mutant group of colorectal cancer cell lines." (PMID 36295658, 2022). "The study group consisted of 20 patients with BRAFMUT advanced colorectal cancer, while 36 patients who had advanced colorectal cancer but who did not have the genetic mutation (BRAF wild-type, BRAFWT) were included as controls." (PMID 34877621, 2022). "Furthermore, Weisenberger’s group also identified the tight association between BRAF mutation and CIMP in colorectal cancers." (PMID 35910024, 2022). "Interestingly, PIK3CA mutations do not feature among the molecular abnormalities conferring resistance to specific BRAF inhibitors in colorectal cancer cell lines." (PMID 36295658, 2022).
colorectal cancer (continued). "The IdyllaTMKRAS and NRAS-BRAF Mutation Tests have been developed for the qualitative detection of mutations in KRAS, NRAS and BRAF genes, facilitating the genomic profiling of patients with colorectal cancer." (PMID 35474548, 2022). "Although these observations are based on a small number of cell lines, they suggest that BRAF mutant colorectal cancers with concomitant aberrations increasing oxidative stress could be candidates for combination therapies with NUAK kinases inhibitors." (PMID 36295658, 2022). "BRAF and PIK3CA mutations are observed in a subset of colorectal cancers." (PMID 36295658, 2022). "The current investigation examines a panel of colorectal cancer cell lines with BRAF mutations with or without concomitant mutations in PIK3CA from the CCLE for drug sensitivities and molecular dependencies." (PMID 36295658, 2022). "Survival of colorectal cancer patients of the TCGA was not different in the groups with BRAF and PIK3CA mutated or both genes mutated compared with cancers with both genes being wild type (Log Rank p = 0.9)." (PMID 36079062, 2022). "An additional key observation of the current report is that BRAF mutated colorectal cancers with or without PIK3CA mutations display lower prevalence of APC mutations than colorectal cancers with wild type BRAF." (PMID 36079062, 2022). "Also, a class II BRAF inhibitor regorafenib, can seemingly reverse resistance to immunotherapy in colorectal cancer." (PMID 36058945, 2022). "The most frequent amplified locus in colorectal cancer at chromosome 20q11.21 is observed exclusively in cancers with wild type BRAF, with or without mutations in PIK3CA (in about 10% of cases in TCGA, not shown)." (PMID 36079062, 2022). "Mutations in the tumor suppressor APC are more prevalent in BRAF wild type colorectal cancers independently of the presence or absence of concomitant PIK3CA mutations in both cohorts (Fisher’s exact test p < 0.0001 for the comparisons in both cohorts)." (PMID 36079062, 2022). "Consistently, in the DFCI cohort, the highest prevalence of MMR/proof-reading polymerases mutations is in double BRAF and PIK3CA mutant colorectal cancers with the exception of POLE which shows the highest mutation prevalence in BRAF mutant cancers without PIK3CA mutations." (PMID 36079062, 2022). "A high prevalence of MSI and CIMP is observed in BRAF mutated colorectal cancers with or without PIK3CA mutations." (PMID 36079062, 2022). "In advanced colorectal cancer, all the patients with MAP2K1 mutation treated with anti-EGFR, anti-EGFR combined with MEK and BRAF inhibitors, or anti-EGFR combined with ERK inhibitors, showed disease progression, where the MAP2K1 mutation was associated with poor response to targeted therapy." (PMID 35186740, 2022). "In contrast to KRAS mutations, mutations of the gene encoding for the catalytic sub-unit alpha of kinase PI3K, PIK3CA, which are common in colorectal cancer are not mutually exclusive with BRAF mutations." (PMID 36079062, 2022). "Studies using patient-derived colorectal cancer organoids to compare BRAF fusions with various fusion partners (TRIM24, AGAP3, and DLG1) have shown that the 5′ partner plays a role in signaling and localization that affects signaling pathways and gene expression." (PMID 35326655, 2022). "Indeed, the BRAF mutant colorectal cancer cell lines that show vulnerability to WRN knock-down are all MSI high, suggesting that this is the underlying molecular defect directly responsible, rather than BRAF mutations." (PMID 36295658, 2022). "Interestingly, GALNT6 mRNA expression showed significant correlation with KRAS and BRAF status in early-stage colorectal cancers." (PMID 35692787, 2022). "Indeed, 21 of 24 BRAF and ATM mutated colorectal cancers (87.5%) in TCGA are MSI or POLE subtype while among BRAF mutated, in ATM wild type cancers only 55.3% belong to these subtypes (Fisher’s exact test p = 0.01)." (PMID 36079062, 2022).
colorectal cancer (continued). "We clinically validated the limit of blank (LOB) and the limit of quantification (LOQ) of assays for the clinically most relevant somatic variants BRAF p.V600E and KRAS p.G12/p.G13 in colorectal cancer (CRC) in a study cohort encompassing a total of 212 plasma samples." (PMID 35159118, 2022). "The chromosomal instability (CIN) pathway is usually driven by sequence mutation events, the most common being KRAS, which leads to typical aneuploid microsatellite stable (MSS) colorectal cancer, and the sequence mutation event that drives CIN is more likely to be KRAS than BRAF." (PMID 35387659, 2022). "Colorectal cancer is known to often develop through a specific number of events along the so‐called conventional pathway, which is a multistep process initiated by mutations in APC, KRAS or BRAF genes." (PMID 35383926, 2022). "This was also observed in the DFCI cohort, where BRAF mutant colorectal cancers with or without concomitant PIK3CA mutations presented less often as stage III or IV than colorectal cancer with both genes on a wild type configuration." (PMID 36079062, 2022). "The BRAF mutation frequency ranges from 4% to 11% but the majority of BRAF mutations were not the V600E, the most prevalent one in colorectal cancers." (PMID 35565398, 2022). "A total of 2311 patients with metastatic or recurred colorectal cancers underwent BRAF testing." (PMID 35625987, 2022). "Compared with colorectal cancer patients without BRAF mutations, BRAF mutant colorectal cancer patients in the TCGA cohort presented at a more advanced age." (PMID 36079062, 2022). "The prognosis of BRAF mutated colorectal cancers with or without PIK3CA mutations is not significantly different than counterparts with wild type BRAF." (PMID 36079062, 2022). "Unlike the canonical adenoma-carcinoma sequence, SPs are proven to be early precursors to about 15%–30% colorectal carcinoma (CRC) through serrated pathway, frequently associated with BRAF or KRAS oncogenic mutations, microsatellite instability (MSI), and high CpG island methylator phenotype (CIMP)." (PMID 35402217, 2022). "Significantly fewer double-mutant colorectal carcinoma cases were classified as BRAF class 1 and more were classified as unknown." (PMID 35280113, 2022). "Moreover, cmFOLFOXIRI in combination with anti-EGFR monoclonal antibody (cetuximab) is recommended as the first-choice conversion therapy for left-sided colorectal cancer patients with wild-type RAS/BRAF." (PMID 34567559, 2021). "BRAF mutation has been proven to predict the efficacy of targeted drugs in the treatment of colorectal cancer and is an independent negative factor affecting the clinical efficacy of bevacizumab added to chemotherapy." (PMID 34925539, 2021). "This study found that doublet therapy for metastatic BRAF variant colorectal cancer was unlikely to be cost-effective under current pricing." (PMID 33433598, 2021). "Our results may provide evidence of an AREG-targeting strategy in patients with RAS/BRAF wild-type colorectal cancer receiving cetuximab-based chemotherapy." (PMID 34893673, 2021). "For instance, BRAF mutations in colorectal cancers occur only in tumors that do not carry mutations in RAS because both genes involved in the common RAS/RAF/MAPK signaling pathway." (PMID 34336831, 2021).
colorectal cancer (continued). "In contrast, in the present study, AREG-induced cetuximab resistance may be attributed to direct EGFR activation in RAS/BRAF wild-type colorectal cancer." (PMID 34893673, 2021). "We have noted a higher response rate in colorectal cancers with BRAF V600E alteration." (PMID 34369992, 2021). "In addition, such BRAF mutant colorectal cancer was reported to be more common in sporadic microsatellite instability (MSI) -high right-sided colon cancers." (PMID 33903966, 2021). "In contrast, BRAF V600E variant is not detected in most colorectal cancers associated with Lynch syndrome, even if they show MSI-H." (PMID 34185173, 2021). "Results of this study suggest that doublet therapy for metastatic BRAF variant colorectal cancer is unlikely to be a cost-effective treatment under current pricing." (PMID 33433598, 2021). "To directly compare the effects of KRAS and BRAF mutations in a genetic background originally dependent on pathway mutation, we engineered KRAS G12C, G12D, G12V and G13D mutations in colorectal cancer RKO cells where the mutant BRAF V600E allele had been removed." (PMID 34233735, 2021). "However, the known differences between colorectal cancer in patients with Lynch syndrome and those with sporadic MSI-H colorectal cancer, such as the incidence of BRAF V600E variants or methylation status, should be recognized." (PMID 34185173, 2021). "BRAF gene and its proteins play a fundamental role in colorectal cancer (CRC)." (PMID 34440099, 2021). "Evidence coming from other in vitro and in vivo studies demonstrated efficient induction of apoptosis in KRAS or BRAF mutant colorectal cancer cell lines treated with navitoclax in combination with the TORC1/2 inhibitor AZD8055 but not in the wild-type controls." (PMID 33777798, 2021). "Similarly, co-inhibition of autophagy plus MEK1/2 triggered apoptotic cell death in a BRAF-driven colorectal cancer cell line." (PMID 34298710, 2021). "Our results indicated that high baseline plasma AREG levels could predict PFS after first-line cetuximab plus FOLFIRI chemotherapy in patients with RAS/BRAF wild-type colorectal cancer." (PMID 34893673, 2021). "BRAF and KRAS mutations are considered drivers of the formation of serrated colorectal cancers." (PMID 33919924, 2021). "In contrast, BRAF inhibitors were effective in hairy cell leukemia with BRAF mutations but not in colorectal cancer, highlighting the limitations of single gene-based approaches and the importance of clinical trials for targeted therapy." (PMID 34359640, 2021). "However, many gaps remain in our current understanding of the acquired resistance to BRAF inhibition in BRAF mutant colorectal cancer that preclude successful management of the colorectal cancer patients carrying BRAF mutation." (PMID 34639107, 2021). "BRAF mutations are more common in colorectal cancer cases with mismatch repair gene abnormalities, but not in gastric cancer." (PMID 34884530, 2021). "In analyses stratified for molecular subtypes, MIC A/B was associated with a lower risk of KRAS-mutated colorectal cancer (OR: 0.66, 95% CI 0.47–0.93), no proteins were associated with the risk of BRAF-mutated or KRAS-BRAF-wild type colorectal cancer." (PMID 33664295, 2021). "Further, in colorectal cancer, RNF43 mutations were found to associate with BRAF V600E mutation." (PMID 34702444, 2021).
colorectal cancer (continued). "For example, lung and colorectal cancers with mutations in KRAS or BRAF do not respond to treatment with anti-EGFR therapies." (PMID 32087721, 2020). "Overall, the most frequently mutated drug target genes were BRAF for thyroid cancer, FGFR2 for endometrial cancer, EGFR for brain tumors, MGMT for colorectal cancer, FGFR2 and FGFR3 for bladder cancer, NTRK3 for non-small cell lung cancer and NTRK2, FGFR2, EGFR for stomach cancer." (PMID 32111026, 2020). "To assess the degree of variation in genetic alterations of WNT signaling pathway genes, we collated whole exome-sequencing data of BRAF mutant colorectal cancers from three previously published studies, combined with 24 samples that were sequenced in-house (total n = 199)." (PMID 32384699, 2020). "For solid tumors other than colorectal cancer, the usefulness of a differential diagnosis with BRAF V600E mutation has not been reported." (PMID 31286289, 2020). "This novel finding may trigger novel therapeutic approaches for BRAF-mutant MMR-D colorectal cancer patients." (PMID 32670606, 2020). "In addition, we experimentally validated predicted synergy of the BRAF/insulin receptor combination (Dabrafenib/BMS-754807) in 48 colorectal cancer cell lines." (PMID 32487991, 2020). "The results of this study reveal that BRAF mutation is a negative prognostic marker in patients with peritoneal metastases from appendiceal or colorectal cancer scheduled for CRS and HIPEC." (PMID 31571052, 2020). "Colorectal cancer cells harboring KRAS or BRAF mutation show a higher expression of RREB1 compared with tissue samples without KRAS or BRAF mutation." (PMID 32210733, 2020). "In conclusion, cutaneous metastasis of colorectal cancer with BRAF V600E mutation is rare and should not be ignored." (PMID 32481270, 2020). "Therefore, we conclude that the co-mutation of BRAF and APC in colorectal cancers is conducive to an aggressive phenotype." (PMID 32384699, 2020). "Recently, a preclinical study reported that cancer cell-selective toxicity of AA in colorectal cancer with KRAS and BRAF mutation could be enhanced by induction of GLUT-mediated cellular uptake of DHA." (PMID 33071784, 2020). "In 35–43% of MSI-H colorectal cancers, the BRAF V600E mutation is detected, while in colorectal cancers in patients with Lynch syndrome, almost no BRAF V600E mutations are detected even in MSI-H cancers." (PMID 31286289, 2020). "A 55-year-old patient with KRAS and BRAF wild-type advanced colorectal cancer had 100% ATM IHC loss in his tumor, but NGS did not detect an ATM mutation." (PMID 32568634, 2020). "To establish whether the WNT mutational landscape of colorectal cancers differs according to BRAF status, we examined the mutational profile of WNT signaling genes in 512 further colorectal cancers from the Cancer Genome Atlas that were BRAF wild type." (PMID 32384699, 2020). "In order to find out whether BRAF inhibition has an effect on the colorectal carcinoma resistant cell line HT-29, we used sorafenib as BRAF inhibitor." (PMID 33198289, 2020). "MAP2K1 mutation has been identified among subsets of smoking-associated lung carcinomas (mutually exclusive from EGFR, BRAF, KRAS, and NRAS mutations), lung adenocarcinoma in situ and early invasive disease, and KRAS/NRAS/BRAF/PIK3CA wild-type (“quadruple-wild-type”) colorectal carcinomas." (PMID 32483240, 2020). "Finally, the responses to BRAF-targeted therapeutic approaches are variable across tumor types, with limited success of these agents in colorectal cancer, for example." (PMID 31158244, 2019). "Concrete efforts have been carried out in order to describe BRAF gene fusions in colorectal cancer." (PMID 31731495, 2019). "For example, autocrine production of the EGFR ligand TGFA was confirmed to be linked to an increased risk of developing metastasis in colorectal cancer, whereas a feedback activation of EGFR was responsible for the failure of BRAF inhibition in patients carrying the mutation BRAF(V600E)." (PMID 31052457, 2019).